MASTL (microtubule associated serine/threonine kinase like)
Description:
Serine/threonine kinase that plays a key role in M phase by acting as a regulator of mitosis entry and maintenance. Acts by promoting the inactivation of protein phosphatase 2A (PP2A) during M phase: does not directly inhibit PP2A but acts by mediating phosphorylation and subsequent activation of ARPP19 and ENSA at 'Ser-62' and 'Ser-67', respectively. ARPP19 and ENSA are phosphatase inhibitors that specifically inhibit the PPP2R2D (PR55-delta) subunit of PP2A. Inactivation of PP2A during M phase is essential to keep cyclin-B1-CDK1 activity high. Following DNA damage, it is also involved in checkpoint recovery by being inhibited. Phosphorylates histone protein in vitro; however such activity is unsure in vivo. May be involved in megakaryocyte differentiation.
Synonyms: GW; GWL; MAST-L; THC2; FLJ14813; GREATWALL
Tractability: Small molecule: a structure with a bound ligand is known; a high-quality ligand is known; it belongs to a druggable protein family. PROTAC: ubiquitination databases record sites on it; a small molecule that binds it is known.
Target class: Enzyme; Transferase
Gene: Protein-coding gene on chromosome 10 (27,154,425 to 27,187,953, forward strand). Ensembl gene ENSG00000120539.
Subcellular location: Cytoplasm, cytoskeleton, microtubule organizing center, centrosome; Nucleus; Cleavage furrow
Subcellular location (Human Protein Atlas): Nucleoplasm
Pathways (Reactome):
Cell Cycle: MASTL Facilitates Mitotic Progression
Gene Ontology:
Molecular function: kinase activity; protein serine/threonine kinase activity; protein phosphatase 2A binding; ATP binding; protein kinase activity; protein serine kinase activity; transmembrane transporter binding
Biological process: G2/M transition of mitotic cell cycle; regulation of cell cycle; DNA damage response; intracellular signal transduction; regulation of mitotic cell cycle
Cellular component: centrosome; cleavage furrow; nucleoplasm; nucleus; microtubule cytoskeleton
Genetic constraint (gnomAD): Loss-of-function variants: 38 observed, 63.39 expected, observed/expected ratio (o/e) 0.6, 90% interval 0.46 to 0.79. The upper end of that interval is the gene's LOEUF score, 0.79, which puts it in group 3 of 6, group 1 being the genes least tolerant of losing a copy. Missense variants: 825 observed, 928.52 expected, observed/expected ratio (o/e) 0.89, 90% interval 0.84 to 0.94. Synonymous variants: 276 observed, 335.44 expected, observed/expected ratio (o/e) 0.82, 90% interval 0.75 to 0.91.
Gene-disease validity (ClinGen):
ClinGen rates the evidence that MASTL causes each of these diseases.
thrombocytopenia (autosomal dominant): Limited. A reduction in the number of circulating thrombocytes.
Homologues: Orthologues: chimpanzee MASTL (99% identical), macaque MASTL (97% identical), pig MASTL (84% identical), rabbit MASTL (84% identical), dog MASTL (79% identical), rat Mastl (75% identical), mouse Mastl (75% identical), tropical clawed frog mastl (53% identical), zebrafish mastl (47% identical), Drosophila melanogaster gwl (32% identical). Paralogues in human: MAST1 (18% identical), MAST2 (18% identical), MAST4 (17% identical), MAST3 (17% identical), LATS1 (16% identical), LATS2 (16% identical), SGK1 (13% identical), SGK2 (13% identical), SGK3 (12% identical), DMPK (12% identical), STK32B (11% identical), STK32C (11% identical), and 1 more.
Diseases named in the same sentence as MASTL in open-access papers:
MASTL is named in the same sentence as 38 diseases in open-access papers, as found by Europe PMC text mining. Sharing a sentence is not in itself a finding about the gene and the disease. The quoted sentences say what the papers report.
breast carcinoma (18 papers, 2015 to 2025). "We also found that MASTL depletion influenced the transcriptome and proteome of breast cancer cells, affecting genes implicated in cell movement and actomyosin contraction." (PMID 32640605, 2020). "Microtubule-associated serine/threonine kinase-like was reported as a potential target for radiosensitization in non-small cell lung cancer cells and breast cancer cells, and is known to regulate recovery from the S/G2 DNA damage checkpoint." (PMID 33117702, 2020). "Recently, two independent groups showed that MASTL inhibited PP2A activity in breast cancer cells, suggesting that the oncogenic role of MASTL is associated with PP2A inhibition." (PMID 33117702, 2020). "In breast cancer, MASTL overexpression is associated with patient poor prognosis, more advanced clinical stage, and reduced survival." (PMID 31947935, 2020). "In this study, we observed that MASTL was upregulated and associated with poor prognosis in breast cancer tissues." (PMID 29976159, 2018). "To further examine the role of MASTL in the radioresistance associated with breast cancer stem cells (BCSCs), we sorted BCSCs from MCF7 cells by using CD44high/CD24low, a marker for BCSCs." (PMID 29976159, 2018). "MASTL is commonly overexpressed in several cancer types including colon, oral and breast cancer, with overexpression in oral and breast associated with cancer progression." (PMID 29743597, 2018). "With regard to the underlying mechanism, we found that MASTL inhibition caused mitotic catastrophe through PP2A activation in breast cancer cells." (PMID 29976159, 2018). "In breast cancer, MASTL is rarely mutated (0.5%), with overexpression and amplification more commonly observed (~10%)." (PMID 29743597, 2018). "Similarly, the upregulation of MASTL on 10p in breast cancer is intricately linked to the progression of the disease." (PMID 39429474, 2024). "Since our previous reports showed that MASTL depletion causes mitotic catastrophe of breast cancer cells, we next evaluated whether MKI-2 induces mitotic catastrophe." (PMID 34358073, 2021). "We showed that MKI-1 exerted antitumor and radiosensitizer activities through PP2A-mediated c-Myc inhibition in breast cancer models, which suggested that MASTL targeting may be associated with the MASTL-PP2A-c-Myc axis in breast cancer." (PMID 33117702, 2020). "Recent studies indicated that MASTL is overexpressed in several types of cancers, including breast, head and neck, thyroid, and colorectal cancers, and is associated with a poor prognosis, particularly in breast cancer." (PMID 33117702, 2020). "Thus, it appears that the different sensitivity of MASTL inhibition between breast cancer cells and normal cells is associated with the selective induction of mitotic catastrophe between cancer cells and normal cells, which have a greater tolerance." (PMID 29976159, 2018). "MASTL expression was closely associated with tumor progression and poor prognosis in breast cancer." (PMID 29976159, 2018). "The protein and mRNA levels of MASTL were highly overexpressed in breast cancer tissues compared to in normal tissue counterparts and MASTL was associated with breast cancer progression, as determined by the analysis of 79 breast cancer specimens and a public database." (PMID 29976159, 2018). "Injecting MKI-2-sensitized tumors led to increased chromosomal instability and downregulation of the MASTL-ENSA-Aurora A pathway in an orthotopic breast cancer mouse model." (PMID 38129815, 2023). "In breast cancer, MASTL overexpression promoted chromosomal instability, and was correlated with disease progression and poor prognosis." (PMID 36247015, 2022). "Our previous report showed that MKI-1 was an MASTL inhibitor with antitumor activities in breast cancer cells." (PMID 34358073, 2021). "We previously reported MASTL kinase inhibitor-1 (MKI-1), a new MASTL inhibitor, showing antitumor activities across in vitro and in vivo tumor models by inhibiting MASTL in breast cancer cells." (PMID 34358073, 2021).
breast carcinoma (continued). "MASTL inhibition reduces the oncogenic properties and enhanced the radiosensitivity of breast cancer cells." (PMID 34358073, 2021). "Recent studies suggested that MASTL acts as an oncogenic kinase by inactivating tumor suppressive PP2A-B55 complex in breast cancer cells, thereby regulating various oncogenic properties, such as cellular transformation, chromosome instability, and metastasis." (PMID 34358073, 2021). "Inhibition of MASTL in colon cancer cells induced chemosensitivity to 5‐FU with downregulation of Survivin and Bcl‐xL expression, whereas MASTL depletion in breast cancer cells enhanced the radiosensitivity with increased PP2A activity." (PMID 32692487, 2020). "Several in silico studies have investigated the perturbation of MASTL through a network biology approach, highlighting a potential therapeutic benefit from MASTL inhibition in neuroblastoma and supporting investigations in breast cancer." (PMID 32640605, 2020). "MASTL has recently been shown to regulate actin cytoskeletal architecture in interphase normal mammary epithelial and breast cancer cells and in post-mitotic platelets." (PMID 32640605, 2020). "Collectively, our data indicated that N-1H-benzimidazol-2-yl-3-(1H-pyrrol-1-yl), a benzamide compound, named as MKI-1, was a new candidate MASTL inhibitor in breast cancer cells." (PMID 33117702, 2020). "Here, we identified and evaluated the compound MKI-1 as a new-line MASTL inhibitor with antitumor activity against breast cancer cells and minimal effects on normal breast cells." (PMID 33117702, 2020). "Several studies showed that MASTL is highly overexpressed in multiple cancers, including breast cancer, compared with normal tissues." (PMID 33117702, 2020). "We also analyzed MASTL expression in two other sets of breast cancer including hormone receptor-positive (n = 73; 12.5 years of follow-up) and triple-negative (TNBC; n = 84; 11.7 years of follow up] breast tumors." (PMID 29229993, 2018). "MDA-MB-231 cells were chosen as they are a well-established highly invasive breast cancer cell line, which overexpress MASTL approximately threefold compared with MCF10A cells." (PMID 29743597, 2018). "We also observed consistently increased MASTL expression in breast cancer tissues and cell lines that was correlated with tumor stage and poor prognosis." (PMID 29976159, 2018). "Taken together, these results indicated that MASTL knockdown prevents invasion in the metastatic MDA-MB-231 breast cancer cell line." (PMID 29743597, 2018). "This study showed the oncosuppressive mechanism of MASTL targeting that promotes mitotic catastrophe through PP2A activation selectively in breast cancer cells." (PMID 29976159, 2018). "Although several studies have recently reported that MASTL inhibition reduces tumor growth in vitro and in vivo, the antitumor mechanism of MASTL targeting in breast cancer cells is still unclear." (PMID 29976159, 2018). "The ability of MASTL to enhance metastasis has to our knowledge, not been previously reported, and likely explains the poor DMFS seen in breast cancer patients that overexpress MASTL." (PMID 29743597, 2018). "Further, we confirmed that high MASTL expression was correlated with poor levels of overall, recurrence-free, and metastasis-free survival in comparison with breast cancers with low MASTL expression." (PMID 29976159, 2018). "MASTL knockdown or knockout using RNA interference or CRISPR/Cas9 systems impairs proliferation of a subset of breast cancer cells." (PMID 29229993, 2018). "As MASTL depletion induces G2 arrest and multiple mitotic defects in somatic cells, we assumed that MASTL depletion induced mitotic cell death in breast cancer cells." (PMID 29976159, 2018). "A similar enrichment of high MASTL expression was also observed in the METABRIC TCGA breast cancer cohort, with ~44% of basal cases overexpressing MASTL." (PMID 29743597, 2018).
breast carcinoma (continued). "Here we show that MASTL overexpression predicts poor survival and shows prognostic value in breast cancer patients." (PMID 29229993, 2018). "Previous reports have indicated that MASTL is overexpressed in several cancer types, with overexpression in breast cancer correlating with poor patient outcomes." (PMID 29743597, 2018). "Collectively, our data suggested that MASTL inhibition was able to suppress the radioresistance of breast cancer stem cells through the promotion of radiation-induced mitotic catastrophe." (PMID 29976159, 2018). "Interestingly, overexpression of mitotic genes along with high levels of CIN are linked with resistance to paclitaxel in breast cancer, suggesting that overexpressed MASTL could potentially be used as a biomarker for resistance to paclitaxel and other mitotic chemotherapies." (PMID 30555827, 2018). "As cancer stem cells are a key factor in the radioresistance of breast cancer cells, we also determined if MASTL inhibition modulated the stemness of breast cancer cells in response to irradiation." (PMID 29976159, 2018). "We found that MASTL depletion predominantly induced cell death and reduced cell viability in breast cancer cell lines, such as MCF7 and T47D." (PMID 29976159, 2018). "Here we provide additional evidence supporting that MASTL overexpression acts as a novel driver of breast cancer, capable of increasing CIN, invasion and metastasis." (PMID 29743597, 2018). "Taken together, these results indicate that MASTL is a novel breast cancer oncogene capable of over-coming contact inhibition, invasion and chromosome instability (CIN)." (PMID 29743597, 2018). "The effects of MASTL depletion with siRNAs were evaluated in various breast cancer cells or normal cells." (PMID 29976159, 2018). "To examine the effect of MASTL depletion on the oncogenic properties of breast cancer cells, we first checked the effect of depletion on anchorage-independent cell growth." (PMID 29976159, 2018). "Our data on breast cancer patients indicates that high levels of MASTL protein correlates with tumor aggressiveness and predicts poor survival in two independent cohorts of ER + tumors, in line with the conclusions from a recent report using mRNA data." (PMID 29229993, 2018). "Taken together, these results support the role that MASTL is a novel breast cancer oncogene capable of driving CIN, invasion and metastasis, which results in more aggressive breast tumours and reduced patient survival." (PMID 29743597, 2018). "Our data showed that MASTL targeting reduced breast cancer cell growth through the promotion of mitotic catastrophe by PP2A activation." (PMID 29976159, 2018). "Here we show that MASTL knockdown or knockout using RNA interference or inducible CRISPR/Cas9 models results in impaired proliferation of some breast cancer cell lines." (PMID 29229993, 2018). "To further validate this, we next determined the dependence of malignant breast cancer cells on MASTL overexpression." (PMID 29743597, 2018). "In support, knockdown of MASTL in the TNBC MDA-MB-231 breast cancer cell line, blocked tumor growth and metastasis in vivo." (PMID 30555827, 2018). "Taken together, these results suggest that MASTL overexpression contributes to chromosome instability and metastasis, thereby decreasing breast cancer patient survival." (PMID 29743597, 2018). "Analysis of MASTL expression in human tumors showed increased levels of the MASTL mRNA in breast cancer compared to normal tissue, correlating inversely with recurrence-free survival in ER-positive breast tumors." (PMID 29229993, 2018). "provides additional evidence that the upregulation of MASTL may be crucial in breast cancer progression." (PMID 39429474, 2024). "Elucidating the links between hnRNPM and MASTL may give a greater understanding to the role MASTL plays in regulating EMT in breast cancer." (PMID 35732702, 2022).
breast carcinoma (continued). "Thus, our data reports a novel MASTL inhibitor for development as a small molecule inhibitor for therapy in MASTL-overexpressed cancers, such as breast cancer." (PMID 34358073, 2021). "In addition, MKI-2 can induce the mitotic arrest phenotype of breast cancer cells, which were identical to the phenotype of MASTL-depleted breast cancer cells." (PMID 34358073, 2021). "Therefore, this study presents a new potent and selective MASTL inhibitor MKI-2 targeting MASTL-PP2A in breast cancer cells." (PMID 34358073, 2021). "Therefore, our study provided a new potent and selective MASTL inhibitor MKI-2 targeting the oncogenic MAST-PP2A axis in breast cancer cells." (PMID 34358073, 2021). "MKI-2 showed nM range potency and efficacy for MASTL inhibition in breast cancer cells." (PMID 34358073, 2021). "Since MASTL can regulate non-muscle myosin IIB expression and myosin activity by increasing phosphorylation of myosin light chain in interphase breast cancer cells, it would be interesting to study if MASTL could affect cell rounding via myosin activation." (PMID 32640605, 2020). "Hence, our data have provided a new-line inhibitor of MASTL with antitumor and radiosensitizing activities in breast cancer." (PMID 33117702, 2020). "MASTL has been proposed as a novel therapeutic target in different tumor contexts; more interestingly, its inhibition sensitizes squamous cancer cells to cisplatin, colon cancer cells to 5-fluorouracil, and lung and breast cancer cells to radiation therapy." (PMID 31947935, 2020). "MASTL inhibition also reduced tumor growth and metastasis in vitro and in vivo in breast cancer." (PMID 33117702, 2020). "We also determined whether MKI-1 increased aberrant nuclei in MCF7 cells, as we had previously observed that MASTL depletion increased aberrant nuclei such as nuclei with irregular shapes or fragmented nuclei in breast cancer cells." (PMID 33117702, 2020). "MASTL is overexpressed in prostate, head and neck, colon, and breast cancer." (PMID 31947935, 2020). "Similar studies in breast cancer have demonstrated that MASTL expression correlates significantly with increased CIN, mitotic index, histological grade, poor overall survival and with a high risk of metastatic relapse in estrogen receptor (ER) positive patients." (PMID 32692487, 2020). "In addition, our data showed that MKI-1 inhibited various oncogenic properties, such as cancer stemness, which phenotype was consistent to the effect of MASTL depletion in breast cancer cells." (PMID 33117702, 2020). "Interestingly, mammosphere formation was reduced after MASTL depletion by siRNA #4 and #5 siRNA in MCF7 and T47D cells, which suggested that MASTL inhibition was able to reduce the oncogenic properties of breast cancer cells with high MASTL expression." (PMID 29976159, 2018). "Next, we checked whether MASTL depletion induced cell death in several breast cancer cell lines, including MCF7, T47D, HCC1937, and SKBR3 cells." (PMID 29976159, 2018). "We therefore hypothesized that MASTL activity could also contribute to breast cancer progression through the inactivation of these complexes." (PMID 29229993, 2018). "Moreover, we also observed that MASTL depletion increased the radiation-induced PP2A activation, suggesting that MASTL inhibition enhances radiosensitivity of breast cancer cells through PP2A activation." (PMID 29976159, 2018). "In addition, clonogenic analysis also indicated that MASTL depletion decreased colony formation of MCF7 and T47D cells, which indicated that MASTL inhibition enhanced the radiosensitivity of breast cancer cells." (PMID 29976159, 2018). "Hence, our data provide evidence for an oncosuppressive mechanism through MASTL targeting that promotes mitotic catastrophe through PP2A activation in the treatment of breast cancer cells, including by radiotherapy." (PMID 29976159, 2018).